LYVE1 (lymphatic vessel endothelial hyaluronan receptor 1)
Diseases named in the same sentence as LYVE1 in open-access papers (continued):
Sharing a sentence is not in itself a finding about the gene and the disease.
tumor (continued). "Based on their similar adhesive functions, LYVE1 and CD44 may both contribute to metastatic spread of cancer cells since HA is more abundant in the surrounding stroma than in the tumor itself." (PMID 20374665, 2010). "In contrast, in the BC and CRC liver metastases with a replacement growth pattern, LYVE-1 expression in the sinusoids of the liver parenchyma that made contact with the tumour cells was not attenuated." (PMID 15054467, 2004). "Both the apparent loss of LYVE-1 expression and the gain of CD34 expression indicate paracrine interactions between tumour cells and co-opted endothelial cells, yet without eliciting angiogenesis or desmoplasia." (PMID 15054467, 2004). "Surprisingly, the numbers of both lymphatic (LYVE-1) and vascular (CD34) vessel counts significantly increased after PRRT treatment, suggesting the activation of a compensatory mechanism that may support tumor survival." (PMID 41012550, 2025). "In addition, more CD8+ T cells are found in tumors lacking LYVE-1+ macrophages, suggesting that LYVE-1+ macrophages have anti-inflammatory functions within the tumor microenvironment." (PMID 38717149, 2024). "Since GFP is a trackable marker, tumor-residing GFP+/CD11b+/Lyve-1+ cells that lacked T-cell and erythroid markers were clearly derived from an initially positive subset generated in vitro rather than from unknown precursors." (PMID 38640116, 2024). "Depletion of LYVE-1+ macrophages correlates with increased apoptosis compared with control mice specifically at the margin, with no changes observed between genotypes in the tumor core." (PMID 38717149, 2024). "Multicolor murine imaging studies indicated that reporter-labeled stroma initially encircled clumps of tumor cells and then served as a scaffold that supported nestin-GFP-labeled endothelial haptotaxis resulting in encircling lymphangiogenesis, confirmed by dual LYVE1 immunofluorescence." (PMID 39669476, 2024). "Interestingly, high LYVE1 expression was observed in both peri-tumor and tumor tissues of non-fibrotic liver, while CD31 was over-expressed in fibrotic liver." (PMID 34983554, 2022). "However, the anti-LYVE-1 antibody is not available in some cases because it can also recognize embryonic hematopoietic stem cells and macrophages in tumor microenvironment." (PMID 34847944, 2021). "Interestingly, the tumor formed by KYSE30-Lenti-miR-548k cells shown increased levels of microlymphatic vessel density (MLD) compared with the control tumors, both peri-tumoral and intra-tumoral tissues, as indicated by the LYVE-1-positive microvessels." (PMID 30131072, 2018). "LYVE-1 was found to be expressed in the liver sinusoids but absent from the tumor." (PMID 24963215, 2014). "LYVE-1 was hypothesized to have an effect that is similar to CD44 on blood endothelial cells, which is facilitated by interacting with tumor cell surface HA and influences tumor cell adhesion." (PMID 23717428, 2013). "It should be noted that this LLC tumor model was characterized by absence of intratumoral lymphangiogenesis in the primary tumors of wildtype mice; however, scant LYVE-1 positive lymphatic vessels were found surrounding the tumors at the time of lymph node harvest." (PMID 21172016, 2010). "However, histological evaluation of the LNCaP tumours demonstrated no LYVE-1-positive lymphatic vessels within the tumour with lymphatic vessels only present in the regions away from the tumour." (PMID 19436293, 2009). "The complement system has many functions in innate immunity including the clearance of apoptotic debris, thus it is possible that the increase in apoptotic cells in the tumor margin may be due to reduced apoptotic cell clearance in the absence of LYVE-1+ macrophages." (PMID 38717149, 2024).
tumor (continued). "In contrast to the high levels of TIM4 expression in LYVE-1+ macrophages in the normal mammary gland, TIM4 expression in LYVE-1+ macrophages from tumors was limited, suggesting that there may be different origins between mammary gland and tumor LYVE-1+ macrophages." (PMID 38717149, 2024). "In the PBS and DOX + AL groups, a clear increase in LYVE-1-positive lymphatic endothelia could not be confirmed within the tumor tissues in the marginal sinus, and LYVE-1-positive littoral cells covering the inner surface of the marginal sinus had virtually disappeared." (PMID 31519920, 2019). "In addition, we found that the presence of LYVE-1-positive cells (lymphatic vessels), MPO- positive cells neutrophils and CD206-positive cells macrophages was significantly increased in the orthotopic xenograft tumours of 44As3 in comparison to those of HSC-44PE." (PMID 31147602, 2019). "Previous reports have shown CD11b+ myeloid cells express LYVE-1 and Prox-1 only when attached to the tumor vasculature but not unattached, indicating that vascular-immune interactions might play a prominent role in the expression of these proteins in the immune cells." (PMID 24124909, 2013). "In cases of invasive squamous cell carcinoma of the uterine cervix, LVD, as assessed by the lymphatic markers D2-40, LYVE-1, and PROX1, did not correlate with LN metastasis, FIGO stage, or tumor grade." (PMID 35885529, 2022). "The ECs-related genes such as ANGPT2, CD34, LYVE1, VWF and PECAM1 were highly upregulated in the vascularized tumor tissue as compared to non-vascularized tissue due to the presence of BVs." (PMID 34754042, 2021). "LYVE-1-positive cells were present in peritumoral areas but not in tumors, therefore all CD31+ structures observed within tumor sections represented the blood vessels." (PMID 23251384, 2012). "Stainings of LN sections for LYVE-1, Prox1, and the proliferation marker Ki67 confirmed that the LEC proliferation rate was increased both in the subcapsular sinus and the medullary sinus of 4T1 tumor-draining, but not non-draining, LNs." (PMID 30590031, 2018). "Furthermore, lymphangiogenic factors LYVE-1 and VEGF-D showed no relation with T stage, N stage, tumor recurrence or distant metastasis." (PMID 25141859, 2014). "Furthermore, we confirmed that CCBE1 was co-localized with CD31 (a marker of vascular endothelial cells), but not with LYVE-1 (lymphatic vessel endothelial hyaluronan receptor 1, a marker of lymphatic endothelial cells), by IHC in serial sections of GIST tumor tissues." (PMID 27506146, 2016). "Moreover, LYVE-1 gene expression followed a similar pattern, and mouse VEGF-C and VEGF-D mRNAs were induced by NCoR depletion, suggesting again that the absence of this corepressor induces changes in the tumor cells that affect the tumor microenvironment." (PMID 27806339, 2016).
cancer (73 papers, 2007 to 2025). A tumor composed of atypical neoplastic, often pleomorphic cells that invade other tissues. "Because metastasis is the leading cause of cancer-related death, we next examined the contributions of LYVE-1+ macrophages to metastasis in the lung." (PMID 38717149, 2024). "MCF-7 miR-146a-5p-OE tumors had fewer cancer cells metastasis, which was associated with less Lyve-1 expression (less lymphangiogenesis) in draining lymph nodes." (PMID 39742358, 2024). "Serum low LYVE-1 levels have been significantly associated with the occurrence of distant metastases in some cancers." (PMID 36672361, 2023). "LYVE1-expressing macrophages have been shown to have a role in maintaining a proangiogenic perivascular niche in cancer, and CCL2 is the primary chemokine responsible for the recruitment of angiogenic macrophages." (PMID 40647416, 2025). "In summary, we show that LYVE-1+ TAMs, and their expression of HO-1, represent an immunotherapeutic target in cancer progression." (PMID 40768602, 2025). "LYVE-1 is frequently overexpressed in various cancers, where it is considered a poor prognostic indicator." (PMID 40507943, 2025). "While the exact role of LYVE-1 in cancer progression is not fully understood, some evidence points to its involvement in lymphangiogenesis and the development of lymph node metastases." (PMID 40507943, 2025). "Research related to LYVE-1 and cancer has primarily focused on its role in the lymphatic system and the immune responses it participates." (PMID 38791985, 2024). "LYVE-1+ macrophages have also been identified in numerous tissues including the lung and aorta, as well as murine models of cancers such as MMTV-PyMT and melanoma tumors." (PMID 38717149, 2024). "Accordingly, LYVE-1 is a potential target for the therapeutic blockade of both immune based disorders and cancer metastasis." (PMID 37606814, 2024). "Targeting LYVE1 has demonstrated therapeutic potential by impairing cancer-related vasculature growth and reducing metastasis." (PMID 37744339, 2023). "Cancer cells manipulate the chemotactic interaction between Lyve-1 and HA to migrate towards lymphatic vessels." (PMID 36158182, 2022). "Second, the discovery and characterization of several biomarkers including VEGF-C, LYVE-1, Podoplanin and Prox-1 have opened new vistas in the understanding of the induction of lymphangiogenesis by cancer cells." (PMID 34767139, 2022). "LYVE1 has been studied extensively for its possible role in cancer diagnosis and prognosis in cancer." (PMID 33717664, 2021). "Our results, consistent with the previous studies, indicated that CD276, IL1B, LYVE1 and VEGFC are associated with cancer progression." (PMID 33995379, 2021). "The 8-mRNAsi based prognostic model in our signatures includes RGS16, LYVE1, hnRNPC, ANP32A, AIMP1, ZNF66, PIK3R3, and MAP2K7, in which several genes have been reported to be linked with stemness features or be involved in cancer progression." (PMID 33329703, 2020). "The soluble form of LYVE-1 (sLYVE-1) is produced by ectodomain shedding of LYVE-1 under pathological conditions including cancer and chronic inflammation." (PMID 31346234, 2019). "Some studies showed that lymphatic endothelial cells of malignant tumors had specific expression of LYVE–1." (PMID 29162097, 2017). "Lymphatic vessel invasion was identified as the presence of cancer emboli within the channels lined by LYVE-1-positive vessels." (PMID 19738610, 2009). "Double labeling of the bladder cross-sections with LYVE-1 and Ki-67 antibodies indicated cancer-induced lymphangiogenesis." (PMID 18047671, 2007). "Upon examining the expression levels of 2 additional HA receptors, RHAMM (encoded by the Hmmr gene) and LYVE-1 (encoded by the Lyve1 gene), we found that LYVE-1 expression was also elevated in mesenchymal cancer cells, whereas RHAMM expression was slightly higher in epithelial cancer cells." (PMID 40178908, 2025).
cancer (continued). "Additionally, subclustering revealed a distinct population of LYVE1+ angiogenic macrophages, previously found in several cancer subtypes." (PMID 40647416, 2025). "LYVE-1+ macrophages have also been identified in breast and other cancer types." (PMID 38717149, 2024). "Interestingly, the lymphatic marker LYVE1 has been found to be involved in immune and cancer cell migration." (PMID 37744339, 2023). "Besides binding to hyaluronan, LYVE-1 can mediate adhesion of leukocytes and cancer cells to endothelial cells." (PMID 36496412, 2022). "In addition, the shed ectodomain of LYVE1 expressed on M2 cells inhibited cancer cell proliferation." (PMID 33995379, 2021). "LYVE1 was thought to contribute to lymphangiogenesis in malignant tumors." (PMID 33329703, 2020). "The PDPN-expressing cells within the matrigel plugs were predominantly co-immunolabeled with the LEC marker LYVE1 but did not express the cancer-associated fibroblast marker αSMA." (PMID 30592710, 2018). "Moreover, the levels of VEGFC and lymphatic endothelial cell marker LYVE-1 expression were also up-regulated in the cancer tissues." (PMID 29717026, 2018). "To date, LYVE-1 is one of the most widely used marker for LECs in normal and cancer tissues." (PMID 25891418, 2015). "In particular, the interaction between LYVE1 and HA on the cell surface may play a role in the diversity of adhesion to cancer cells." (PMID 25403569, 2014). "Interestingly, the expression of LYVE1 alone can significantly explained the survival rates in 4 other cancer types, namely BLCA, LGG, THCA, and UCEC." (PMID 25403569, 2014). "Certain HAIMs, including CD44, TSG-6, LYVE-1, RHAMM, HAPLN3, NCAN, and VCAN, can facilitate the proliferation of cancer cells." (PMID 38791985, 2024). "In fact, LYVE1, VEGF-C and ITGA9 are among the most down-regulated genes from the low LV signature patients among all the different cancer types analyzed." (PMID 35663931, 2022). "These cell populations were further analyzed by using Lamp1PM expression in combination with a set of canonical markers distinct for cancer and stromal cells (i.e., desmin, Ki67, Sca1, Sma, Pcam1, CD44, Lyve1, and EpCam)." (PMID 36127469, 2022). "Lyve-1 and other LEC markers have been consistently detected in M2-TAMs in mouse tumors and cancer patients." (PMID 35442077, 2022). "Ectonucleoside triphosphate diphosphohydrolase 1 (ENTPD1) is positively correlated with LYVE1, PDPN, and VEGFC in the LECs of patients with different cancers." (PMID 36067135, 2022). "While this model has been used by others to study the functional contributions of LYVE-1+ macrophages to the maintenance of arterial tone, it has not previously been used to assess LYVE-1+ macrophage function in cancer models." (PMID 38717149, 2024). "The LYVE-1 expression pattern implies the transfer of HA from tissues into the lymphatic vessel, where it is internalised and degraded and provides a chemotactic substrate for CD44+ leukocytes and cancer cells." (PMID 38791985, 2024). "HA is one of the biopolymers used for cancer cell-specific targeting because overexpressed cancer cell receptors such as cluster determinant 44 (CD44), hyaluronan receptor for endocytosis (HARE), and lymphatic vessel endothelial hyaluronan receptor-1 (LYVE-1) are reactive to the HA." (PMID 33467616, 2021). "LYVE1 is reported to be elevated in urine of patients with PDAC, enough to be one of three biomarkers to stratify cancer risk, with no data on cachexia." (PMID 33334063, 2020). "Finally, four key genes (KLHL30, PLN, LYVE1, and TIMD4) and four clinical factors (Asian, age, grade, and bilirubin) were included in the prognostic model, namely Immunity and Cancer-stem-cell Related Prognosis (ICRP) score." (PMID 32852285, 2020). "While LYVE-1 on LECs and macrophages has been shown to internalize HA prior to degradation by hyaluronidases, this function has not previously been described in the context of cancer." (PMID 38717149, 2024).
cancer (continued). "Moreover, the cancer tissue expressions of CD31, LYVE-1 and CD206 were detected by IHC." (PMID 27172798, 2016). "Lymphatic vessel density was determined by LYVE-1-positive vessels without cancer emboli." (PMID 19738610, 2009).
infection (14 papers, 2009 to 2025). The state of being infected such as from the introduction of a foreign agent such as serum, vaccine, antigenic substance or organism. "LNs from WT CHIKV but not attenuated CHIKV 181/25–infected mice displayed a reduced and spatially altered expression of Lyve1 by 48 hours after infection as well as a loss of MARCO expression, suggesting that WT CHIKV infection disrupts Lyve1+ LECs." (PMID 38194268, 2024). "At 8 and 24 hours after infection, Lyve1 and MARCO expression were similar across dLNs from mock-, CHIKV 181/25–, and WT CHIKV–infected mice." (PMID 38194268, 2024). "Infection of Lyve-1-Cre and Prox1-CreERT2 mice revealed that amongst EC subsets, infection of lymphatic ECs was sufficient." (PMID 36689486, 2023). "For this purpose, we injected α-LYVE-1 antibody every 2 days to ensure the receptor was neutralised until day 10 post-infection." (PMID 37870927, 2023). "Intranasal infection of WT mice with VAC∆C7L leads to a marked increase of IMs (especially Lyve1− IMs), and a modest increase of CD11b+ DCs in the infected lungs." (PMID 35351885, 2022). "Consistent with that, lung monocytes isolated from mice at day 3 post-infection contained more infectious virions compared with Lyve1− IMs, suggesting that Lyve1− IMs are more efficient in eliminating either WT VACV or VACV∆C7L than monocytes." (PMID 35351885, 2022). "This further implicates the lymphatic system as a major conduit and focus for infection in domestic animals, possibly through an interaction with equine LYVE-1." (PMID 26352587, 2015). "Consistent with the published results, infection of HUVECs with KSHV led to a significant increase in the expression of XLKD1/LYVE1, VEGFR-3 and PROX-1, while treatment of HUVECs-K13-ERTAM with 4OHT failed to do so." (PMID 19660139, 2009). "qRT-PCR analysis also showed that the angiogenesis-related genes, Angpt1, Id1, and Lyve1, were significantly upregulated at 10 weeks post-infection, and Pecam1 was significantly upregulated at 10–12 weeks post-infection." (PMID 41334166, 2025). "However, by 48 hours after infection, Lyve1 signal was greatly reduced and MARCO signal was undetectable in dLNs from WT CHIKV–infected mice." (PMID 38194268, 2024). "In order to visualize the location of M18 GAS in the lymph nodes draining the site of infection, the same intra-muscular thigh infection model was used, and inguinal lymph nodes from both wildtype C57Bl/6 and LYVE-1-/- were dissected and sectioned at the 3 hour time-point." (PMID 26352587, 2015). "This hypothesis is supported by our observation that relatively few M18 GAS were recovered from lymph nodes draining the muscle infection site in LYVE-1-/- mice compared with their wildtype counterparts." (PMID 26352587, 2015). "We found that by 24 hpi in virus-infected bite sites, there was a selective loss of Lyve1+F4/80+CD11b+ cells, whereas numbers did not decrease in bite sites in the absence of virus, suggesting that they had been depleted after infection with this often cytolytic virus." (PMID 27332734, 2016). "These parallels with CD44 raise the possibility that LYVE-1 could play a role in sensing HA complexes generated during inflammation in vivo, allowing the lymphatics to decode the status of interstitial matrix in injury or infection." (PMID 26823460, 2016). "After infection with enhanced green fluorescent protein (EGFP)-expressing SFV, we found large numbers of EGFP+Lyve1+ cells in the dermis." (PMID 27332734, 2016). "Following infection via an intra-muscular route, the dissemination of encapsulated M18 GAS was compared between LYVE-1-/- mice and age and sex matched wildtype controls by quantitative culture." (PMID 26352587, 2015). "(F) Infection leads to a selective reduction in LYVE1 immunostaining, and little or no change in CD206 immunostaining, in macrophages in the leptomeninges and dura." (PMID 37318981, 2023).